IL6 (interleukin 6)
Diseases named in the same sentence as IL6 in open-access papers (continued):
Sharing a sentence is not in itself a finding about the gene and the disease.
depression (continued). "IL-6 is one of the most consistent biomarkers of depression, with elevations observed in circulating levels, and is associated with treatment resistance." (PMID 39335629, 2024). "The primary outcome will be shoulder function and the secondary outcomes will include pain intensity, shoulder ROM, interleukin-6 (IL-6), depression, anxiety, and quality of life (QoL)." (PMID 38689290, 2024). "The overproduction of pro-inflammatory cytokines, such as tumor necrosis factor-alpha and interleukin-6, has been observed in cases of depression." (PMID 38424581, 2024). "There is a great deal of correlational evidence that patients who suffer from anxiety and depression show elevations in circulating levels of cytokines that are pro-inflammatory in nature, such as Tumor necrosis factor alpha, IL-1β, IL-6, and IL-17." (PMID 38255692, 2024). "Elevated levels of other inflammatory cytokines such as Interleukin-1 beta (IL-1 β), Interleukin-2 (IL-2), and Interleukin-6 (IL-6) have also been observed in patients with major depressive disorder compared to healthy controls." (PMID 38959212, 2024). "Brexanolone reduced baseline levels of the inflammatory markers TNF-α and IL-6, and these effects predicted improvement in the Hamilton Rating Scale for Depression (HAM-D) scores." (PMID 38792602, 2024). "Serum IL-6 was associated with HAMA, Hamilton Depression Scale (HAMD), the Unified MSA Rating Scale I (UMSARS I) scores, the UMSARS IV and the Instrumental Activity of Daily Living scores." (PMID 39295596, 2024). "Elevated levels of pro-inflammatory cytokines, such as interleukin-6 (IL-6), have been observed in patients with anxiety and major depressive disorders." (PMID 39295939, 2024). "According to a recent meta-analysis of cytokines in major depression, the proinflammatory cytokines IL-6 and TNF-α were significantly increased in depressed subjects when compared to healthy controls." (PMID 38674048, 2024). "Acute hyper-hypoxia plays an important role in the development of depression via the IL-6/PGC1α/MFN2 signaling pathway." (PMID 39135980, 2024). "Converging evidence from research in human patients and corresponding animal models of the disease suggests that the proinflammatory cytokine interleukin 6 (IL6) plays a role in the pathophysiology of depression." (PMID 38855751, 2024). "A meta-analysis demonstrated that interleukin-6 (IL-6), C-reactive protein (CRP), and tumor necrosis factor-α (TNF-α) are the inflammatory factors most closely associated with depression." (PMID 38877455, 2024). "Stress-induced depression in humans is accompanied by a decrease in claudin-5 expression and an increase in IL-6 expression." (PMID 38898454, 2024). "This also explains the increase in 5-HT content, decrease in pro-inflammatory factors TNF-α and IL-6 content, and increase in anti-inflammatory factor IL-10 content in the serum of mice with depression-like behavior after oral administration of asiaticoside." (PMID 39494347, 2024). "Increased levels of proinflammatory mediators and markers, such as CCL2, CRP, and IL-6, were found in patients with severe depression." (PMID 38931342, 2024). "Numerous studies have reported a significant correlation between increased tumor-related fatigue and depression with elevated expression of pro-inflammatory cytokines IL-1β and IL-6 mRNA in the cortex and hippocampus." (PMID 38716256, 2024). "The same study also reported that exogenous ghrelin inhibits the endothelial cell production of IL-1, IL-6, and IL-8 by regulating the release of pro-inflammatory cytokines, which play an important role in the pathologic process of depression." (PMID 39057075, 2024). "Two studies have employed this strategy and performed univariable MR analysis examining the effect of IL6 trans signaling on depression-related sleep-problems/disorders." (PMID 38511149, 2024).
depression (continued). "Heartfulness practice was associated with decreased depression, anxiety, and stress scores and improved health measures in DHEA-S and IL-6 levels." (PMID 39680432, 2024). "Increased inflammation, as indicated by IL-6 levels at age 9 years, provides a potential mechanistic explanation for this link, even when controlling for depression." (PMID 39038862, 2024). "The injection of IL-6 in the amygdala induces depression-like behaviors, and mice hyper-expressing IL-6 showed increased excitability of the central nucleus of the amygdala." (PMID 38248262, 2024). "A study of depression found that increased IL-6 levels were correlated with dysconnectivity of a brain functional network." (PMID 39358787, 2024). "Inflammatory cytokines, notably interleukin 6 (IL-6), are regarded as the endogenous biomarker and therapeutic target for depression." (PMID 38632601, 2024). "Research have claimed that Alistipes has a pathogenic effect on colorectal cancer through the IL-6/STAT3 pathway and has been linked to depression." (PMID 38774867, 2024). "In the next step, the concentrations of zinc, albumin a, CRP, and IL-6 were compared between the groups of patients with unipolar depression (UD), bipolar depression (BDD), and the group of healthy subjects (HC)." (PMID 38785543, 2024). "We have derived a novel, multi-protein biomarker of IL-6 activity/bioavailability in a sample of patients with an ICD-10 diagnosis of depression." (PMID 38442505, 2024). "Depression and well-being score associations with complement component 3 (CES-D only) c-reactive protein, interleukin 6, leptin, white blood cell counts, neutrophils and the inflammatory biomarker score were observed." (PMID 38560580, 2024). "FMT from patients with RA into the ABX-treated mice resulted in depression-like behavior, changed gut microbiota composition, elevated levels of IL-6 and TNF-α, and downregulated levels of synaptic proteins in the PFC." (PMID 38983862, 2024). "Next, IL-6 knockout MRL/lpr (IL-6 KO; n = 15) and IL-6 wildtype MRL/lpr mice (IL-6 WT; n = 15) underwent behavioral testing, focusing on murine correlates of learning and memory deficits, depression, and anxiety." (PMID 38600510, 2024). "In elderly patients, increased serum levels of IL-1β and IL-6 in depression and increased levels of IL-1β, as well as microglial activation markers in AD, are reported." (PMID 38796643, 2024). "Increased cytokines that initiate the inflammatory cascade, such as interleukin-1 Beta (IL-1β), IL-6, and tumor necrosis factor (TNF), have been associated with severe depression linked to stress." (PMID 39335507, 2024). "Patients with severe depression and animal models of depression often exhibit elevated levels of pro-inflammatory cytokines such as IL-1β, IL-6, and TNF-α." (PMID 38628641, 2024). "The secondary objective is to evaluate the effectiveness of an 8-week LLLT versus MET compared to CTE on pain intensity, shoulder ROM, interleukin 6 (IL-6), depression, anxiety, and QoL." (PMID 38689290, 2024). "Some studies have indicated that elevated levels of C-reactive protein (CRP) and interleukin-6 (IL-6) in diabetic patients are closely related to the worsening of symptoms and increased depression levels in patients with schizophrenia." (PMID 39421064, 2024). "Certain cytokines are elevated in persons with depression as well as RA, including IL-1β, IL-6, and TNF-α." (PMID 38340224, 2024). "Clinical studies have shown that the levels of IL-1, IL-6, TNF-α, and IFN-α are generally elevated in SS patients; therefore, some people believe that SS is a cause of depression and anxiety." (PMID 39479595, 2024). "The review also highlights the involvement of inflammatory markers, such as Interleukin 6 (IL-6) and leptin, in PD and Major Depressive Disorder (MDD) patients." (PMID 39025836, 2024). "Elevated IL6 activity can potentially induce depression via stimulation of the hypothalamic–pituitary–adrenal axis or modulation of neurotransmitter metabolism." (PMID 38297317, 2024).
depression (continued). "For example, studies included in a meta-analysis found an association between increased levels of IL-1RA, IL-6, IL-10, IL-12, sIL-2R, sIL-6R, and TNF-α, and decreased levels of IFN-γ and IL-4, in adult patients with depression." (PMID 38474387, 2024). "The study explored the correlation between pro-inflammatory cytokines such as TNFα, IL-1β and IL-6 with hippocampal volume and scores on the Beck Depression Inventory." (PMID 38377025, 2024). "A diet containing both doses of the anthocyanin-enriched functional ingredient with a low DII but high DAQ-S was found to improve anxiety, depression, and stress, with changes in 8-OHdG and IL-6 levels." (PMID 39682956, 2024). "Statistical analyses indicate a positive correlation between depression and IL-1 and IL-6, with body mass index (BMI) potentially serving as a mediating/modulating factor." (PMID 39329797, 2024). "Meanwhile, some inflammatory cytokines secreted by the musculoskeletal system are closely related to the occurrence of depression, such as IL-6, TNF-a, and 5-HT." (PMID 39161853, 2024). "For major depression, a decrease of interleukin (IL)-6 serum levels based on the treatment with SSRIs has been shown before, eliciting possible anti-inflammatory mechanisms of SSRIs besides the increase of serotonin." (PMID 38796643, 2024). "Altered levels of cytokines and chemokines are reported in neurological and psychiatric disorders, and for depression, psychotherapy, and antidepressants reduced levels of IL-6." (PMID 38931342, 2024). "Similar effects have been observed in other conditions, such as major depressive disorder, where a four-week course of probiotics significantly reduced IL-6 gene expression in patients with depression." (PMID 39595910, 2024). "Several studies have shown that the activation of the kynurenine (KYN) pathway in patients with depression is secondary to increased levels of the inflammatory cytokines interleukin (IL)-6, interferon (IFN)-α and tumor necrosis factor (TNF)-α." (PMID 39654767, 2024). "The intervention of Astragalus polysaccharide (APS) significantly reduced the levels of hippocampal TNF-α, IL-1β, and IL-6 in rats with CUS-induced depression." (PMID 38389919, 2024). "When considering potential mechanisms behind the pathogenesis of depression, it is worth mentioning that IL-6 has an inhibitory effect on the serotonin transporter (SERT), which plays a crucial role in regulating serotonin levels in the CNS." (PMID 39273641, 2024). "Serum levels of proinflammatory cytokines such as IL-1, IL-6, and tumor necrosis factor alpha are elevated not only in the patients with depression but also in COPD patients." (PMID 38386662, 2024). "TNF-α, IL-1β and IL-6 promote depression and inhibit the functional activity of serotonergic neurons." (PMID 38898454, 2024). "In depression research, the inflammatory cytokines IL-6 and TNF-α have been strongly correlated with the pathology and severity of major depression, and the role of oxidative stress in the progression of depression has long been appreciated." (PMID 39158617, 2024). "Individuals with depression, for instance, frequently show elevated levels of pro-inflammatory cytokines—such as IL-1β, IL-6, and TNF-α—in their blood and cerebrospinal fluid." (PMID 39273641, 2024). "Maternal infection, anxiety, or depression are associated with increased levels of pro-inflammatory cytokines, including TNF-α, IL-1β, and IL-6, not only in the maternal circulation but also in the fetal circulation and CNS." (PMID 38726788, 2024). "Elevated levels of pro-inflammatory cytokines (including Tumor Necrosis Factor-alpha (TNF-alpha) and Interleukin 6 (IL-6)) influence brain function, leading to depression, anxiety, and anger in humans." (PMID 39061510, 2024). "We also report associations between single inflammatory proteins and somatic symptoms (IL-6, CRP), fatigue (CRP), and depression severity (IL-6, CRP)." (PMID 38442505, 2024).
depression (continued). "Using data from 86 patients with International Classification of Diseases-10 diagnosis of depression, we calculated a ratio score representing IL-6 activity/bioavailability using serum IL-6, soluble IL-6 receptor (sIL-6R), and soluble glycoprotein 130 levels." (PMID 38442505, 2024). "IL-6 KO mice showed improvement in learning and memory with unaltered murine correlates of depression or anxiety." (PMID 38600510, 2024). "The results of the study showed that SNPs of eNOS, HSP70, FKBP5, miR-146a, ACE2, MAS1, SGK1, IL-4–589, IL-6–174, TNF-α–308, CRP–717, 5-HTTLPR, and BDNF genes are associated with the comorbidity of coronary heart disease and depression." (PMID 38745947, 2024). "Increased expression of the cytokine IL6, in both peripheral and central systems, is believed to play a vital role in stress reactions and depressive disorders, especially as a comorbidity with physical illnesses." (PMID 38297317, 2024). "In relation to depression, it has been established that TNFα, as do IL-1 and IL-6, induces not only symptoms of physical sickness but also major depressive disorders in physically ill patients with no previous history of mental disorders." (PMID 39358787, 2024). "Elevated IL-6 levels have been observed in individuals with depressive disorders, impacting serotonin metabolism within the central nervous system." (PMID 39850107, 2024). "The aim of our study was to investigate the role of pro-inflammatory IL-6, TNF-α, and IL-1β and anti-inflammatory IL-10 and TGF-β in depressive disorders observed in patients suffering from pain caused by disk herniation (DH) qualified for surgery." (PMID 38646609, 2024). "Previous studies of IL-6 in CSF from patients with depression compared to healthy controls included 32 patients as a maximum." (PMID 37016363, 2023). "Depression-related increases in pro-inflammatory cytokines, such as IL-6 and TNF, can, on one hand, further stimulate HPA and glucocorticoid release." (PMID 38067176, 2023). "More studies on large samples are needed to verify the usefulness of serum BDNF and IL-6 as biomarkers of depression and antidepressant treatment response in children." (PMID 34590201, 2023). "Previous research has demonstrated that major depressive disorder patients are in a proinflammatory state, with elevated levels of innate immune plasma mediators such as IL-6, TNF-a, and C-reactive protein." (PMID 37924045, 2023). "Maternal immune activation was shown to result in anxiety- and depression-like behaviors, cognitive impairment, and increased levels of proinflammatory cytokines, including interleukin (IL)-1β, IL-6, and tumor necrosis factor-alpha (TNF-α) in offspring." (PMID 37560531, 2023). "Cytokines, such as interferon-γ (IFNγ), C-reactive protein (CRP) and IL-6, increase with chronic stress, correlate with the severity of depression and predict cognitive changes in depression." (PMID 37836393, 2023). "The odds ratio of a higher preoperative serum IL-6 level was measured to be 9.76, indicating that ENS patients with a higher serum IL-6 level would have a nearly 10-fold risk of developing severe depression." (PMID 37324195, 2023). "For example, medical illnesses that cause increases in inflammatory factors such as interleukin-6 (IL-6), tumor necrosis factor-α (TNF-α), and C-reactive protein (CRP) increase the risk for depression." (PMID 37840796, 2023). "Increased levels of cytokines such as IL-6, IL-10, IL-12, IL-13, and IL-17 were found in individuals with depression." (PMID 37240864, 2023). "Associations between polymorphic variants of the IL1B, IL6, and TNFA genes were the most replicated and relevant in depression." (PMID 37510364, 2023). "Proinflammatory mediators, particularly interleukin (IL)-2, IL-6, IL-12, and tumor necrosis factor-alpha (TNF-α) have been linked to the progression of depression in past studies." (PMID 37353760, 2023).
depression (continued). "Increased inflammatory cytokines in the brain and in serum, such as CRP, and soluble cell-adhesion molecules IL-6, IL-1β, TNF-α and NF-κB, would be involved in the susceptibility to depression in stressed obese mice." (PMID 37836393, 2023). "Studies should also assess the levels of other inflammatory markers such as IL-6, TNF-α and their association with postoperative depression." (PMID 37928924, 2023). "The relationship between the severity of psychological problems (depression, anxiety and stress) and the serum level of interleukin 6 in patients with COVID-19." (PMID 37692307, 2023). "For example, patients with depression often exhibit elevated levels of inflammatory markers like C-reactive protein and IL-6, and anti-inflammatory drugs can improve depressive symptoms." (PMID 37492530, 2023). "According to the neuroinflammatory theory of depression, IL-6 and BDNF remain closely related, as chronic neuroinflammation is considered to cause a decrease of BDNF level in the brain." (PMID 34590201, 2023). "Depression is associated with inflammation by increasing C-reactive protein (CRP) and cytokines, such as interleukin-6 (IL-6) and tumor necrosis factor-α (TNF-α)." (PMID 37096248, 2023). "If the researchers have slimmed their options to IL-6 or CRP, they would want to decide which protein to target based on which protein is most strongly associated with depression." (PMID 37393056, 2023). "A meta-analysis examining the relationship between depression and inflammation in children and adolescents found that depression was significantly associated with elevated levels of CRP and IL-6." (PMID 37840796, 2023). "The impact of pro-inflammatory cytokines such as TNF-α, IL-1β, IL-6, and IL-8 on depression has been widely studied." (PMID 38025419, 2023). "Vitamin D modulates proinflammatory cytokines, such as IL-6 and TNF-α, linked with systemic inflammation in depression and suicidal tendencies." (PMID 37762207, 2023). "Only one cytokine-symptom connection remained, IL-6—observed depression (r = 0.01); and this was reliable (appearing in 56% of bootstrapped procedures)." (PMID 37723153, 2023). "Supporting this, increased levels of proinflammatory cytokines including IL-1β and IL-6 and decreased levels of anti-inflammatory cytokines including IL-4 and IL-10 have been detected in people living with depression." (PMID 38053532, 2023). "After exercise intervention, the plasma levels of IL-1β, IL-6, and TNFα in patients with depression were significantly reduced, and depressive symptoms were improved." (PMID 37511879, 2023). "The IL-6, Geriatric Depression Scale-15 items version (GDS-15) score, and Mini-Mental State Examination (MMSE) score increased in both groups." (PMID 36911130, 2023). "Increased inflammatory markers were measured in patients with major depressive disorder: IL-1β, IL-6, TNF-α, and CRP." (PMID 36899845, 2023). "AGP1 is increased in plasma during the acute phase of depression, in which it positively correlates with high concentrations of IL-6 and C-reactive protein (CRP)." (PMID 38049858, 2023). "Interleukin-6 (IL-6) is one of the inflammatory markers most closely and consistently related to depression." (PMID 37304432, 2023). "Elevated IL-6 levels in plasma are linked to depressive symptoms in COPD, independent of airflow limitation and comorbid risk factors for depression." (PMID 37048736, 2023). "We also concluded that increased levels of inflammatory markers (CRP, IL-6, PCT, D-dimer, and serum ferritin) were associated with increased prevalence of psychiatric manifestations like depression." (PMID 37621784, 2023). "Compared with healthy controls, the levels of interleukin-4, interleukin-6, and interleukin-10 changed significantly in major depressive disorder patients." (PMID 37275977, 2023). "Cancer patients who present with depression also have raised blood IL-6 and an increase in daily cortisol." (PMID 36787313, 2023).